RHOB (ras homolog family member B)
Diseases named in the same sentence as RHOB in open-access papers (continued):
Sharing a sentence is not in itself a finding about the gene and the disease.
Myelodysplasia (2 papers, 2009 to 2013). Clonal hematopoietic stem cell disorders characterized by dysplasia (ineffective production) in one or more hematopoietic cell lineages, leading to anemia and cytopenia. "In this study, we hypothesized that the myelodysplasia observed in Drf1-null mice would be enhanced by the additional loss of one of its regulators, RhoB." (PMID 19768111, 2009). "Here, we show that the additional knockout of RhoB expression in Drf1-null mice accelerates the progression to myelodysplasia." (PMID 19768111, 2009). "Mice lacking RhoB alone do not show any signs of myelodysplasia or any developmental or fertility defects, but Ras-transformed mouse embryonic fibroblasts (MEFs) from these mice are resistant to apoptosis in the presence of farnesyltransferase inhibitors (FTIs), doxorubicin, or taxol." (PMID 19768111, 2009).
ovarian adenocarcinoma (2 papers, 2013 to 2019). An adenocarcinoma that arises from the ovary. "Couderc and colleagues restored RhoB in ovarian adenocarcinoma cells with undetectable levels of RhoB, leading to suppression of tumor growth." (PMID 31200451, 2019).
Stroke (2 papers, 2013 to 2016). Sudden impairment of blood flow to a part of the brain due to occlusion or rupture of an artery to the brain. "Following neutralizing NogoA antibody delivery, massive overactivation of the small Rho GTPases Rac1 and RhoB was noticed when the antibody was administered prior to stroke, the former of which overactivated the stress kinases p38 and Jun kinase-1/2 (JNK-1/2) thus activating cell death pathways." (PMID 27547178, 2016). "Through bio-informatic analysis, we found that stroke related genes RhoB and beclin-1 might be the targets of miR-30a." (PMID 24237608, 2013).
triple-negative breast carcinoma (2 papers, 2020 to 2024). An invasive breast carcinoma which is negative for expression of estrogen receptor (ER), progesterone receptor (PR), and human epidermal growth factor receptor 2 (HER2). "Restoration of the breast cancer 1 (BRCA 1) gene expressions in BRCA1-mutant triple-negative breast cancer cell lines can increase the expression of RHOB, resulting in reduced migration capacity." (PMID 39376611, 2024). "As RhoA and RhoB seem to have antagonistic roles in triple negative breast cancer, we studied the cellular effects of specific inhibition of RhoA or RhoB by siRNA." (PMID 33162807, 2020). "Taken together, these data suggest a higher RhoA/RhoB expression ratio in triple negative breast cancer cells but the comparison of 2 luminal cell lines to 5 triple negative cell lines is not very statistically relevant." (PMID 33162807, 2020). "In these data, the expression of RhoA was approximately equivalent in the two groups but RhoB was much lower in the triple negative breast cancers." (PMID 33162807, 2020).
viral infection (2 papers, 2017 to 2021). "RhoB is not only a component of the human cytomegalovirus (HCMV) assembly complex but is also required for productive viral infection." (PMID 34834920, 2021). "The immunity-related proteins Mib1, RhoB and Gbp5 became more abundant in macrophage lysosomes after treating with L. m, HSV-1 or VSV, while lysosomal Oasl2 (Viperin) was augmented by both virus infections." (PMID 28088779, 2017).
acute lung injury (1 paper, 2022). A condition of lung damage that is characterized by bilateral pulmonary infiltrates (pulmonary edema) rich in neutrophils, and in the absence of clinical heart failure. "In human acute lung injury (ALI), the activation of RHOB potentiates the TLR4/NF-κB signaling pathway activity, resulting in the release of inflammatory factors." (PMID 36231106, 2022).
acute lymphoblastic leukemia (1 paper, 2023). Leukemia with an acute onset, characterized by the presence of lymphoblasts in the bone marrow and the peripheral blood. "Conversely, an overexpression of RHOB has been reported in T-acute lymphoblastic leukemia (T-ALL) compared to primary human T cells, suggesting that the functions of this GTPase might be context- and tumor-dependent." (PMID 36766776, 2023).
Arthritis (1 paper, 2017). Inflammation of a joint. "Together, these data suggest that RhoB is essential for programming the pathogenic character of the autoantibody repertoire mediating arthritis in this model system, potentially acting as a unique molecular determinant in autoimmune disease." (PMID 28882929, 2017). "In this study, we show how RhoB acts as a positive modifier of disease in the development of pathogenic autoantibodies required to drive arthritis in K/BxN mice, an established preclinical model of autoimmune disease." (PMID 28882929, 2017). "Histological examination of ankles from RhoB ko KRN.g7 mice confirmed a reduction in arthritis as measured by reduced synovial expansion, inflammatory cell infiltrates, and cartilage and bone erosion." (PMID 28882929, 2017). "In contrast, anti-RhoB-Ig-treated mice exhibited a significant attenuation in arthritis development, both at the time of onset and in terms of overall severity." (PMID 28882929, 2017). "As an important control we confirmed that anti-RhoB Ig attenuated arthritis severity in wt KRN.g7." (PMID 28882929, 2017). "Importantly, anti-RhoB Ig remained effective at attenuating arthritis even when it was administered after the onset of arthritis, suggesting its use both prophylactically and therapeutically." (PMID 28882929, 2017). "To determine whether anti-RhoB Ig could inhibit autoantibody production, we employed the established K/BxN murine model of arthritis that is mediated by high titers of anti-GPI autoantibodies." (PMID 28882929, 2017). "Thus, one possible explanation for the reduced arthritis observed in the RhoB ko KRN.g7 mice, despite their high autoantibody levels, was that RhoB was critical at the effector stage of arthritis occurring after autoantibody production." (PMID 28882929, 2017). "Although the endpoint of reduced disease severity was shared when RhoB was targeted by genetic deletion or with an antibody, the mechanism by which arthritis was attenuated may be different." (PMID 28882929, 2017). "To determine whether RhoB ko mice were able to develop arthritis, we made use of the serum-transfer model of arthritis." (PMID 28882929, 2017). "Strikingly, we found that serum transfer from RhoB ko KRN.g7 mice failed to induce arthritis in wt recipient mice, compared to serum transferred from wt KRN.g7 mice, which caused disease." (PMID 28882929, 2017). "Consistent with results from anti-RhoB-antibody-treated mice, development of arthritis in RhoB ko KRN.g7 mice was delayed and attenuated, but not fully ablated, relative to wt KRN.g7 mice." (PMID 28882929, 2017). "If RhoB was critical for pathogenic autoantibody production, then serum transferred from the ko KRN.g7 mice should not induce arthritis, even though it contained anti-GPI autoantibodies." (PMID 28882929, 2017). "To validate RhoB as the target and establish whether RhoB was required for the effect of anti-RhoB Ig, we evaluated arthritis and autoantibody production in RhoB ko KRN.g7 mice, in which arthritis is diminished compared with KRN.g7 mice but not fully absent." (PMID 28882929, 2017). "Therefore, our results showing that autoantibody levels were not reduced in RhoB ko KRN.g7 mice, but arthritis was attenuated, seemed paradoxical." (PMID 28882929, 2017).
autoimmune disease (1 paper, 2017). A disorder resulting from loss of function or tissue destruction of an organ or multiple organs, arising from humoral or cellular immune responses of the individual to their own tissue constituents. "In summary, our observations using two different preclinical autoimmune models suggest a function for RhoB in specifically mediating the production of pathogenic autoantibodies, which contribute to autoimmune disease." (PMID 28882929, 2017). "In the MRL/lpr mouse model of systemic lupus erythematosus (SLE), another established preclinical model of autoimmune disease associated with autoantibody production, administration of the anti-RhoB antibody also reduced serum levels of anti-dsDNA antibodies." (PMID 28882929, 2017). "Overall, our results highlight a newly identified function for RhoB in supporting the specific production of pathogenic autoantibodies, and offer a preclinical proof of concept for use of anti-RhoB Ig as a disease-selective therapy to treat autoimmune disorders driven by pathogenic autoantibodies." (PMID 28882929, 2017). "Based upon this line of reasoning, we asked whether administering the anti-RhoB Ig might shut down antibody secretion in a preclinical mouse model of autoimmune disease, where autoantibody production serves as a pathogenic driver, as well as in the context of an immune response to a model antigen." (PMID 28882929, 2017). "Collectively, our findings offer an early illustration of how an anti-RhoB antibody may be useful for the study and treatment of autoimmune disorders driven by the production of pathogenic autoantibodies, including RA, SLE, myasthenia gravis and type 1 diabetes." (PMID 28882929, 2017). "Our work suggests that RhoB is a new therapeutic target for the treatment of autoantibody-mediated autoimmune diseases." (PMID 28882929, 2017). "To address the potential for model-specific effects to explain our observations, we determined whether administration of anti-RhoB Ig could similarly affect autoantibody levels in the MRL/lpr model of SLE, as a second established model of autoimmune disease." (PMID 28882929, 2017). "Together, our findings suggest the utility of RhoB as a molecular probe to explore fundamental questions about the development of self versus non-self and the mechanisms controlling the emergence of autoimmune disorders." (PMID 28882929, 2017).
autoimmune disorders (1 paper, 2017). "In a second preclinical model of autoimmunity, the MRL/lpr model of systemic lupus erythematosus (SLE), administration of anti-RhoB Ig also selectively diminished production of anti-double-stranded-DNA (anti-dsDNA) autoantibodies." (PMID 28882929, 2017).
cervical tumors (1 paper, 2019). "RhoB expression is induced by EGF, PDGF, and many other agents, while several factors including N-Ras and EGFR suppress RhoB promoter activity in NIH3T3 cells and human cancer cell lines derived from lung, pancreatic, and cervical tumors." (PMID 31331053, 2019).
Chronic colitis (1 paper, 2022). A chronic inflammatory disease of the large intestine (colon, cecum and rectum). "We subsequently examined the role of RhoB in chronic colitis induced by lower doses of DSS." (PMID 36114582, 2022). "Taken together, these results demonstrate that decreased RhoB has a potent preventive effect on DSS-induced acute and chronic colitis." (PMID 36114582, 2022).
clear cell renal cell carcinoma (1 paper, 2019). "Suppression of RHOB by direct binding of miR-19a or miR-19b on 3′-UTR of RHOB has also been shown to promote cell growth, invasion, and migration in clear cell renal cell carcinoma, while inhibition of miR-19a or miR-19b favors apoptosis induction." (PMID 31200451, 2019).
colorectal tumor (1 paper, 2024). "Taken together, RhoB, HIF1A, Met, MAPK6, and PKM may play key roles in promoting colorectal tumor formation in males." (PMID 38347027, 2024).
COVID-19 (1 paper, 2022). A disease caused by infection with severe acute respiratory syndrome coronavirus 2. "It is also notable that many of the transcriptional signatures, including RHOB, MPP6, TNFRSF1B, ITGB2, and ZEB2 elevated in AM2 from COVID-19 patients have also been detected as transcriptional markers of AM B cells." (PMID 35899045, 2022).
dementia (1 paper, 2024). Loss of intellectual abilities interfering with an individual's social and occupational functions.
dengue (1 paper, 2025). "B7, Bacillus licheniformis, and Clostridium cochlearium, along with the host genes, namely, PPME1, TIMP2, NLRC4, and RhoB, were associated with immune dysregulation in the severe dengue patients." (PMID 41417796, 2025).
diabetic retinopathy (1 paper, 2025). "The RHOB gene encoding Ras homolog gene family, member B protein, and SELENOS have recently been identified as biomarkers for diabetic retinopathy." (PMID 41465472, 2025).
E. coli infection (1 paper, 2021). "Expression of engulfment mediators MARCKS, RhoB, and CDC42 were reduced or unchanged following succinate or lactate treatment and increased in itaconate-treated macrophages following E. coli infection." (PMID 34350128, 2021).
esophageal squamous cell carcinoma (1 paper, 2026). Esophageal squamous cell carcinoma (ESCC) is a type of esophageal carcinoma (EC) that can affect any part of the esophagus, but is usually located in the upper or middle third. "In addition, this study identified RHOB as a novel biomarker for esophageal squamous cell carcinoma and verified that RHOB was associated with proliferation, migration and invasion of ESCC by in vitro cellular assays." (PMID 41972154, 2026).
fibrosarcoma (1 paper, 2022). A malignant mesenchymal fibroblastic neoplasm affecting the soft tissue and bone. "Using the Spearman correlation index, we observed, as expected, that RHOB expression negatively correlated with the hypoxia-induced gene signature in lung, breast and fibrosarcoma tumors, while VIM and ITGB2 expression were generally positively correlated in all three cancer patient cohorts." (PMID 35681731, 2022).
gynecological cancers (1 paper, 2025). "In conclusion, our findings indicate that the expression of 6-CRRGs, including APOBEC3B, HELLS, SLC15A3, CDA, RHOB and UPP1, is associated with the prognosis of patients with common gynecological cancers." (PMID 39944833, 2025). "RHOB was associated with the pathways of ECM receptor interaction, focal adhesion and etc. in all these three common gynecologic cancers." (PMID 39944833, 2025).
head-neck cancers (1 paper, 2024). "On the other hand, RhoB has demonstrated tumor suppressor characteristics by inhibiting cell invasion and metastasis, and enhancing therapy response, leading to better clinical outcomes such as bladder, ovarian and head-neck cancers." (PMID 38355625, 2024).
HIV-1 infection (1 paper, 2022). The type species of lentivirus and the etiologic agent of acquired immunodeficiency syndrome (AIDS). "It is more likely, though, that miR-223 influences HIV-1 infection by targeting cellular factors required for replication, such as ras homolog family member B (RhoB), Sp3 transcription factor (Sp3), and leukemia inhibitory factor (LIF)." (PMID 36142450, 2022). "Therefore, miR-223 may function as a negative factor in HIV-1 infection by reducing RhoB-mediated activation of the AKT–NF-κB pathway." (PMID 36142450, 2022).
kidney cancer (1 paper, 2021). Primary or metastatic malignant neoplasm involving the kidney. "In kidney cancer, overexpression of RhoB significantly inhibits KIRC cell malignant phenotype, which indicated that RhoB play a cancer suppressive role in KIRC cells, raising its potential value in future therapeutic target for the patients of KIRC." (PMID 33761933, 2021).
Listeria monocytogenes infection (1 paper, 2023). "For example, during Listeria monocytogenes infection, miR-21 was upregulated in mice, and miR-21 then targeted MARCKS and RhoB, which depressed L. monocytogenes intracellular replication." (PMID 37239318, 2023).
lymph node metastases (1 paper, 2013). "Enhanced immunoreactivity of all analysed proteins was found to be associated with the presence of lymph node metastases (ezrin, P = 0.047, moesin, P = 0.038, RhoA, P = 0.024, RhoB, P = 0.004 and Cdc42, P = 0.047)." (PMID 23420497, 2013). "In our study, over-expression of RhoA, RhoB and Cdc42 was found to be strongly associated with the presence of lymph node metastases." (PMID 23420497, 2013).
malignant meningioma (1 paper, 2016). "In our hands, targeting of DLC1-v1 with specific shRNA in KT21cells established from human malignant meningioma resulted in enhanced activity of RhoA/RhoB/RhoC GTPases as shown in active RHO pull down assay and increased cell migration in scratch assay." (PMID 27614886, 2016).
mastitis (1 paper, 2022). Inflammation of breast tissue during lactation or postpartum due to an obstructed duct or infection. "Although miR-223 has been identified to regulate RHOB gene expression in humans, the molecular regulatory mechanism in LPS-induced mastitis in cows has not been examined." (PMID 36231106, 2022). "Overall, bta-miR-223 attenuated LPS-induced inflammatory response, and acted as a negative feedback regulator via targeting RHOB, providing a novel avenue for mastitis treatment." (PMID 36231106, 2022).
meningioma (1 paper, 2026). A generally slow growing tumor attached to the dura mater. "Hsa-miR-21-5p enhanced proliferation and viability of KT21-MG1 meningioma cells and showed a regulatory effect on IL6R, IL6ST and other predicted target genes TIMP3, PIK3R, RHOB, and SASH1 by interacting with 3'UTRs." (PMID 42196381, 2026).
metastatic melanoma (1 paper, 2015). A melanoma that has spread from its primary site to another anatomic site. "RHOB expression levels were subsequently analyzed by immunostaining in a retrospective series of 32 biopsies from patients with metastatic melanoma harboring BRAFV600X mutations, receiving PLX4032 as a front-line therapy." (PMID 26098773, 2015). "Supporting these results, loss of RHOB expression in metastatic melanoma tissues is associated with an increased progression-free survival of BRAF-mutant patients treated with vemurafenib." (PMID 26098773, 2015). "Finally, our results on metastatic melanoma biopsies highlight a pivotal role for RHOB in the therapeutic management of this disease." (PMID 26098773, 2015). "We conclude that the basal expression of RHOB in tumor cells may represent a predictive value of PLX4032 response to treatment in BRAFV600X metastatic melanoma." (PMID 26098773, 2015).
neuroblastoma (1 paper, 2025). Neuroblastoma (NB) is the most common solid, extracranial childhood tumor. "Peptideslabeled with Rhodamine-B (RhoB) were readily taken upby SH-SY5Y neuroblastoma cells, as confirmed by live fluorescencemicroscopy and quantification of RhoB-labeled puncta." (PMID 41001629, 2025).
non-small cell lung adenocarcinoma (1 paper, 2022). Type of epithelial lung cancer arising from glandular origin. "In non-small cell lung adenocarcinoma (NSCLC) cells, miR-223 mediated RHOB knockdown and significantly inhibited RHOB protein expression, thereby suppressing the development of NSCLC." (PMID 36231106, 2022).
oral squamous cell carcinoma (1 paper, 2020). "Studies realized for understanding oral squamous cell carcinoma mechanisms and revealed that overexpression of both miR-223 and miR-22 suppressed NLRP3 inflammasome and NF-κB signaling through ras homolog family member B (RHOB) and were considered as potential therapy targets." (PMID 33015196, 2020).
ovarian tumor (1 paper, 2013). "In order to revive the expression loss of RhoB gene, in vitro ovarian tumor growth and treatment responses to HDACi and demethylating agent were observed." (PMID 24223801, 2013).